INS (insulin)
Diseases named in the same sentence as INS in open-access papers (continued):
Sharing a sentence is not in itself a finding about the gene and the disease.
metabolic syndrome (continued). "A reduction in insulin sensitivity alone can predict the metabolic syndrome in adulthood, which in turn is an independent risk factor for later mortality from coronary heart disease and cerebrovascular disease." (PMID 23840881, 2013). "The possibility that the hyperinsulinaemia in individuals who develop metabolic syndrome predisposes towards cancer implicates a direct effect of high plasma insulin concentrations." (PMID 23983688, 2013). "MTTP, which has associations with metabolic syndrome, body mass index, and insulin regulation, showed a strong signature of selection in Southeast Asians, including Indonesians." (PMID 23349834, 2013). "Evaluation of fasting insulin has been highlighted, given that a strong association between basal hyperinsulinemia, blood pressure alterations, and dyslipidemia has been demonstrated." (PMID 23363783, 2013). "Loss of this capacity produces increased uptake in other metabolically less suited tissues such as liver, muscle, and pancreatic beta cells where harmful effects include fatty liver, dyslipidemia, and loss of insulin sensitivity and insulin secretion." (PMID 23766565, 2013). "The metabolic syndrome is associated with altered hormonal profiles for testosterone, insulin, IGFs, and oestrogen, all of which are linked to prostate cancer." (PMID 22548055, 2012). "A genotype/phenotype association was found with fasting glucose and insulin levels as well as predisposition for the development of metabolic syndrome in human populations." (PMID 22680924, 2012). "The molecular relationship between insulin signaling and lipid homeostasis is complex, as dyslipidemia is considered to be both a cause and a consequence of insulin resistance." (PMID 22275878, 2012). "We aimed to assess the effects of psyllium supplementation on insulin sensitivity and other parameters of the metabolic syndrome in an at risk adolescent population." (PMID 22848584, 2012). "In this study, we aimed to investigate the effect of psyllium fibre supplementation alone on insulin sensitivity and other parameters of the metabolic syndrome in an at risk adolescent population." (PMID 22848584, 2012). "In the Atherosclerosis Risk in Communities (ARIC) study, both vWF and FVIII were associated with components of the metabolic syndrome including BMI, plasma insulin levels, and triglyceridemia." (PMID 24278711, 2012). "Using real-time PCR, we validated the expression of Serpin12, an adipokine linked to the metabolic syndrome and insulin sensitivity." (PMID 23342276, 2012). "In particular, physical activity has been widely studied because of its well-known effects on the metabolic syndrome, insulin sensitivity, cardiovascular disease risks, and all-cause mortality." (PMID 22701195, 2012). "Serum adiponectin, osteocalcin and insulin levels were measured, and the association of the components of metabolic syndrome with adiponectin and osteocalcin levels was investigated." (PMID 23261860, 2012). "Cross sectional data have shown that fibre and whole grain consumption in adolescence is associated with increased insulin sensitivity and a lower incidence of the metabolic syndrome." (PMID 22848584, 2012). "In this present study, the effects of vitamin D deficiency on both insulin sensitivity and risk of metabolic syndrome were investigated in a region which is known to have a high incidence of vitamin D deficiency among the adolescents." (PMID 22155462, 2011). "In this study, we found that metabolic syndrome, a potent risk factor for cardiovascular disease, had a prevalence that was more than two times higher in insulin-resistant subjects." (PMID 22025967, 2011). "There are also some reports showing a correlation (mild or very strong) of vitamin D deficiency with metabolic syndrome and insulin sensitivity in children." (PMID 22155462, 2011).
metabolic syndrome (continued). "In the present analyses, we found that accelerated early infant weight gain from birth to three months was also associated with markers of the metabolic syndrome: increased basal insulin levels, HOMA-IR, adverse lipid profile, and hypertension." (PMID 21655104, 2011). "Most studies have demonstrated that insulin levels are associated with other metabolic factors generally clustered within the Metabolic Syndrome." (PMID 21959060, 2011). "Insulin resistance (IR) in patients with metabolic syndrome (MetS), who are at high cardiovascular risk, is associated with impaired insulin signaling via the insulin receptor substrate-2- (Irs2-) AKT2 pathway in mononuclear leukocytes (MLs)." (PMID 22347652, 2011). "Many studies showed that high levels of body mass index (BMI, kg/m2) among children and adolescents were associated with abnormal levels of lipids, insulin, blood pressure and all components of the metabolic syndrome." (PMID 21176200, 2010). "Dietary ratios of omega-3 (n-3) to omega-6 (n-6) polyunsaturated fatty acids (PUFAs) have been implicated in controlling markers of the metabolic syndrome, including insulin sensitivity, inflammation, lipid profiles and adiposity." (PMID 20584300, 2010). "Increased intestinal synthesis of CM and of their major protein component, apolipoprotein B48, have been identified as important contributors to the dyslipidemia associated with insulin-resistant and diabetic states." (PMID 20463919, 2010). "CLA was first described as a potent anti-carcinogenic component and more recently has been associated with improving dyslipidemia, insulin sensitivity and the pro-inflammatory state related to obesity and the metabolic syndrome." (PMID 20633302, 2010). "In multivariable adjusted analyses, the T-allele additionally showed association with lower insulin levels (p = 0 .002); the relationship with metabolic syndrome became insignificant." (PMID 20661421, 2010). "HRR is positively associated with insulin sensitivity as measured with a hyperinsulinemic-euglycemic clamp and metabolic syndrome in elderly men as well as in middle-aged men and women." (PMID 19187547, 2009). "One mechanism by which physical activity lowers the risk of the metabolic syndrome is that participation in even non vigorous activity is associated with higher insulin sensitivity." (PMID 17625024, 2007). "Recent reviews of the literature note that stimulation of insulin release by increased carbohydrates promotes adipogenesis, weight gain and atherogenesis, all associated with the metabolic syndrome." (PMID 17570846, 2007). "Hyperinsulinemia represents a critical target for investigating dietary strategies aimed at reducing the risk of metabolic syndrome, given its assssociation with carbohydrate-induced insulin secretion and its strong link to obesity and metabolic syndrome development." (PMID 41493485, 2026). "On the other hand, although androgens play essential physiological roles in both sexes, elevated androgen levels, especially in females, have been linked to impaired insulin sensitivity and dyslipidemia, thereby increasing the risk of T2DM and related complications." (PMID 41531538, 2026). "Zitzmann15 focused on the relationship between T deficiency, metabolic syndrome (MetS), and CV risk, underscoring that TTh might improve insulin sensitivity, reduce body fat, and enhance lipid profiles." (PMID 40372318, 2026). "Even though obesity is the major risk factor for metabolic syndrome, subjects with normal weight may also be insulin resistant and may have metabolic syndrome." (PMID 40065855, 2025). "Studies have reported that it is also involved in the regulation of glucose and lipid uptake, improvement of insulin production and signaling, inhibition of adipogenesis, reduction of inflammation, and oxidative stress associated with metabolic syndrome, among other processes." (PMID 40313489, 2025).
metabolic syndrome (continued). "Produced primarily in the liver, this multifunctional glycoprotein has been implicated in the regulation of insulin sensitivity, inflammatory processes, and lipid metabolism, which places it as a plausible contributor to the pathophysiology of dyslipidemia and related disorders." (PMID 41007661, 2025). "Furthermore, FABP3 methylation was associated with lipid, insulin, and blood pressure indicators, affecting metabolic syndromes in humans." (PMID 40239869, 2025). "Lipid profile is improved by regular physical activity, since exercise not only enhances lipid metabolism by increasing the activity of fat oxidation enzymes, but also improves insulin sensitivity, which is crucial for mitigating the risk of metabolic syndrome and cardiovascular diseases." (PMID 40077646, 2025). "In addition, SCFAs exert anti-inflammatory effects and help maintain intestinal barrier integrity, mechanisms that have been linked to a reduced risk of metabolic syndrome and improved insulin sensitivity." (PMID 41228439, 2025). "Moreover, altered GLUT2 function is associated with non-alcoholic fatty liver disease and metabolic syndrome, conditions marked by insulin resistance and lipid accumulation in the liver." (PMID 40699693, 2025). "Furthermore, subclinical hypercortisolism was significantly associated with severe T2D, defined by the presence of insulin treatment, hypertension, and dyslipidemia." (PMID 38092990, 2025). "Indeed, a diet enriched with MUFAs prevents or improves metabolic syndrome and the risk of cardiovascular disease, by favorably modulating blood lipids, blood pressure and insulin sensitivity." (PMID 40805652, 2025). "In particular, the deterioration of metabolic health is often accompanied by a cascade of metabolic disturbances—such as insulin resistance, ectopic fat accumulation, and dyslipidemia—that act synergistically to elevate the risk of cardiovascular and metabolic diseases substantially." (PMID 40917090, 2025). "Flaxseed’s ability to stabilize blood glucose levels and enhance insulin sensitivity positions it as a functional food for managing patients with MetS or T2D while simultaneously addressing other cardiometabolic risk factors like obesity and dyslipidemia." (PMID 39821819, 2025). "Moreover, PA enhances insulin sensitivity, improves lipid metabolism, and reduces the risk of obesity, thereby preventing metabolic syndrome (MetS)." (PMID 40705115, 2025). "Furthermore, the study showed that sacubitril+valsartan combination treatment normalised the elevated insulin levels associated with metabolic syndrome." (PMID 41586197, 2025). "Adiponectin, which regulates insulin sensitivity and inflammation, could help identify individuals at higher risk for metabolic syndrome or atherosclerosis." (PMID 40272732, 2025). "Parallelly, the same pathologic mechanisms which underlie the cardiovascular disease associated with human metabolic syndrome, including changes in insulin signaling, inflammatory cytokines, and vascular/endothelial dysfunction, could contribute to laminitis." (PMID 41394912, 2025). "Obesity‐related NAFLD manifestation by metabolic syndrome is a prevalent public health issue, has been consistently linked to a range of disorders comprising dyslipidemia, hypertension, resistance to insulin, and a greater vulnerability to cardiovascular mortality." (PMID 39803213, 2025). "Additionally, the effect of exercise on FLI is likely mediated through mechanisms such as weight loss, reduced insulin resistance, and improvements in HbA1c and atherogenic dyslipidemia associated with metabolic syndrome." (PMID 39136513, 2025). "Sex hormones have been shown to influence insulin sensitivity and risk of metabolic syndrome, which could impact AGE levels." (PMID 40312267, 2025). "Another significant metabolic alteration caused by insulin dysfunction is dyslipidemia." (PMID 41030912, 2025).
metabolic syndrome (continued). "By improving insulin sensitivity and glucose metabolism and reducing inflammation associated with dyslipidemia, PBM could play a role in preventing or slowing AD progression." (PMID 39246604, 2024). "Therefore, we aimed to explore the relationship between dietary insulin indices and dietary pattern with the risk of Metabolic Syndrome (MetS)." (PMID 38263222, 2024). "Thus, muscular fitness has been associated with metabolic syndrome and lipid metabolism in young people, promoting insulin sensitivity and glycemic control and reducing adipose tissue." (PMID 38474733, 2024). "Insufficient insulin secretion in diabetic patients causes an increase in hormone-sensitive esterase activity, which leads to a large release of fatty acids and their accumulation in the body, causing dyslipidemia." (PMID 39678246, 2024). "A longer HFD duration should be tested to develop a more severe metabolic syndrome and highlight some other mechanisms that could be implicated, such as liver alteration and higher insulin resistance." (PMID 38892407, 2024). "This behaviour, however, has been associated with increased visceral adiposity and an increased risk of metabolic syndrome, as irregular meals may negatively influence glycaemic control and insulin response." (PMID 39683619, 2024). "Given that metabolic syndrome is a recognized risk factor for pancreatitis, irbesartan may indirectly elevate the risk of pancreatitis by influencing insulin metabolic pathways." (PMID 39635439, 2024). "We have shown that ATP10A is required to maintain lipid homeostasis and liver insulin sensitivity with HFD feeding, therefore, a therapeutic that acts as an ATP10A agonist could help treat diseases that cause dyslipidemia and hepatic insulin resistance." (PMID 38172157, 2024). "The rate of dyslipidemia is higher in patients on peritoneal dialysis, driven by increased lipoprotein synthesis in the liver due to glucose absorption from the dialysis solution, which increases insulin levels and protein loss." (PMID 39439522, 2024). "Actually, this pig breed has been suggested as animal model for nutrition-associated diseases due to their susceptibility to central obesity, irregularities in insulin-glucose regulation, dyslipidemia, and high blood pressure, all indicative of metabolic syndrome." (PMID 39264906, 2024). "Ath+HFD induces dyslipidemia, lipid peroxidation, and stellate cell activation in the liver and finally causes precirrhotic steatohepatitis after 24 weeks accompanied by cellular ballooning and hepatic insulin resistance." (PMID 38619434, 2024). "Increased VAT correlates with increased serum concentrations of small and dense LDL, low HDL, inflammatory markers, proinflammatory adipocytokine production, impaired insulin sensitivity, dyslipidemia and hypertension, and increased risk of endothelial dysfunction and thrombosis." (PMID 37834099, 2023). "Limited evidence proposed that irisin had the properties of promoting muscle hypertrophy, enhancing insulin sensitivity, alleviating hepatic steatosis and anti-inflammation, and improving metabolic syndrome and CVD, but the underlying mechanism still needs further characterization." (PMID 37180779, 2023). "Similar observations are seen in clinical studies where FMT increased insulin sensitivity in patients with metabolic syndrome and increased haemoglobin in those with anaemia caused by chronic disease by modulating the intestinal microbiota composition and metabolism." (PMID 37858192, 2023). "We next examined whether Tn housing would be sufficient to alter the expression of lipid metabolism- and insulin signaling-associated genes linked with metabolic syndrome in NAFLD." (PMID 36875069, 2023). "postulate that a low human biliverdin, and consequently bilirubin activity, could not only result in unopposed tissue oxidative stress but also cause dysregulation of insulin signaling, which is a hallmark of metabolic syndrome." (PMID 38107514, 2023).
metabolic syndrome (continued). "In this respect, oxidative stress is well-known to be one of the most relevant molecular drivers behind these metabolic disorders, within a complex crosstalk involving other intertwined pathogenic events, such as inflammation, insulin disturbances, and dyslipidemia factors." (PMID 37672200, 2023). "Thus, analyzing the association between the glucagon to insulin ratio and metabolic syndrome in patients with T2DM would indirectly shed light on the effect of glucagon on cardiovascular disease." (PMID 37762748, 2023). "Metabolic syndrome may be associated with muscle loss through a complex interplay of multiple factors, including pro-inflammatory cytokines, insulin resistance, mitochondrial dysfunction and oxidative stress." (PMID 38235492, 2023). "hsa-miR-21-5p was linked, clinically and via in silico proof, to insulin metabolism, inflammation, dyslipidemia, and tumorigenesis in the HCC patients’ group as well as for an upregulated independent risk factor for the emergence of HCC from LC in the CHCV patients." (PMID 36834570, 2023). "Cortisol inhibits insulin release, reduces insulin sensitivity, and causes hypermetabolism, which in turn promotes hypertension, central obesity, and glucose intolerance, all of which contribute to the development of metabolic syndrome." (PMID 38137454, 2023). "However, insulin deficiency caused dyslipidemia due to inhibitory action of insulin on HMG-CoA reductase." (PMID 35620596, 2022). "PCOS is complicated by obesity, insulin resistance (IR), diabetes mellitus, dyslipidemia, and metabolic syndrome, caused by a genetic predisposition to abnormal-excessive steroidogenesis, irregular peripheral insulin sensitivity and lipid metabolism alterations." (PMID 35877459, 2022). "In addition, abdominal obesity is linked to metabolic syndrome, which includes dyslipidemia, hypertension, and abnormal glucose and insulin regulation." (PMID 36553418, 2022). "Insulin signaling via the insulin receptor (IR) may be associated with the amelioration of diet-induced metabolic syndrome." (PMID 36570152, 2022). "Actually, IR precedes the occurrence of T2DM, so how to increase the accurate assessment of insulin sensitivity is very important to predict the risk and evaluate the management of impaired insulin sensitivity and metabolic syndrome in research and clinical practice." (PMID 35794109, 2022). "Another factor that may play a role in DTAC and NAFLD risk reduction is fiber, which contributes to weight loss, improved insulin sensitivity, dyslipidemia, and glycemic control." (PMID 36407541, 2022). "We also show that plasma succinate, which is associated with several components of metabolic syndrome including waist circumference, triglycerides, and uric acid, among others, is a primary determinant of insulin sensitivity evaluated by the euglycemic-hyperinsulinemic clamp." (PMID 36002880, 2022). "In addition to associations related to the vitamin D receptor gene and BsmI genotypes with glycemic markers, low serum concentrations of 25OHD3 have been associated with reduced insulin sensitivity, impaired glucose metabolism, and metabolic syndrome." (PMID 35213542, 2022). "In high concentrations, it trans-differentiates white adipose tissue into brown adipose tissue, possibly promoting weight loss, improving metabolic syndrome parameters, improving insulin sensitivity, and protecting against the development of cardiovascular diseases." (PMID 36362238, 2022). "Similarly, rodent models have demonstrated that possession of ApoE4 increases risk of metabolic syndrome, possibly by interfering in insulin-sensing pathways." (PMID 35409283, 2022). "Nonetheless, its association with insulin sensitivity / resistance / glucose tolerance and metabolic syndrome remains unclear in childhood." (PMID 35065638, 2022). "Insulin dysregulation and dyslipidemias are also a hallmark of equine metabolic syndrome and may contribute to similar pathologies." (PMID 36214464, 2022).